TERC (telomerase RNA component)
Diseases named in the same sentence as TERC in open-access papers (continued):
Sharing a sentence is not in itself a finding about the gene and the disease.
aplastic anemia (11 papers, 2007 to 2023). Anemia resulting from bone marrow failure (aplastic or hypoplastic bone marrow). "In patient MG_5, known for the previous history of aplastic anemia (AA), we found a TERC mutation, known to be associated with AA pathogenesis." (PMID 35836575, 2022). "A high incidence of TERC mutation and an increased copy number of TERC genes has been reported to associate with the pathogenesis of the inherited disorder dyskeratosis congenital (DC), aplastic anemia (AA) and other genetic diseases." (PMID 31294790, 2019). "Two other TERC mutations linked to aplastic anemia and autosomal dominant DC, G107U, and GC107/108AG, likewise disrupt methylation at C106." (PMID 29880812, 2018). "Mutations in telomerase core components, TERT and TERC, have been found in patients suffering from aplastic anaemia and dyskeratosis congenital (DKC), as described later." (PMID 17353922, 2007). "As in DKC-associated aplastic anaemia, a report found mutations in the TERC gene in patients with aplastic anaemia." (PMID 17353922, 2007). "G107U and GC107/108AG are TERC mutations related to aplastic anemia and autosomal dominant DC5,6." (PMID 29880812, 2018). "In the event of TERC haploinsufficiency, telomere length is often affected; this, in turn, can result in the development of progeria-related diseases such as aplastic anemia (AA) and congenital keratosis." (PMID 37424004, 2023). "The incidence of aplastic anaemia is greater in patients with TERC or TINF2 mutations compared to patients with DKC1 mutations, and cancer incidence is highest in patients with TERC mutations." (PMID 21931702, 2011). "The proband (Subject C-III-1), a thirty year-old Caucasian male previously fond to be heterozygous for a TERC nucleotide 28-34 deletion, had a thirteen-year history of moderate aplastic anemia." (PMID 19936245, 2009).
glioma (11 papers, 2015 to 2024). A benign or malignant brain and spinal cord tumor that arises from glial cells (astrocytes, oligodendrocytes, ependymal cells). "Although TERT promoter mutations are extremely rare in pediatric gliomas, increased TERC and TERT expression are associated with decreased ΟS in high-grade tumors." (PMID 38240992, 2024). "The indication of risk alleles for glioma close to TERC and TERT that are also related with telomere length suggests that telomerase is important in glioma formation." (PMID 30483309, 2018). "We recently showed that glioma risk alleles near TERC and TERT are associated with increased leukocyte telomere length (LTL)." (PMID 26646793, 2015). "In addition to the integrated phenotypic and genotypic features of glioma, many genetic studies have found that common inherited variants near several genes (TERC, TERT, EGFR, CDKN2B, PHLDB1 and RTEL1) are associated with increased risk of adult glioma." (PMID 30462709, 2018). "Altogether, our data suggest that NAF1 lengthens telomere length through regulating TERT at both transcription and translation levels and TERC at transcription levels in glioma cells." (PMID 30936423, 2019). "Our single-locus analyses show an association between inherited variation in the telomerase component genes TERC and TERT and glioma risk, as previously reported." (PMID 26646793, 2015). "This suggests that additional LTL-associated SNPs outside the TERC, TERT and RTEL1 regions also confer glioma risk." (PMID 26646793, 2015). "Because the association between glioma risk and LTL remained significant even after excluding the TERC, TERT and RTEL1 SNPs from the LTL calculations, it is unlikely that the association observed in our data could be entirely attributable to pleiotropy." (PMID 26646793, 2015). "In previous genome-wide association studies, researchers have shown that genetic polymorphisms in the telomere-related genes TERC, TERT and RTEL1 are related to increased glioma susceptibility, suggesting that telomere may play an important role in glioma genesis." (PMID 27655710, 2016). "In contrast to the glioma cell line SF188, combined ATRX knockout (KO) and TERC KO led to ALT-like properties and sensitized U251 glioma cells to ATR inhibition in vitro and in vivo." (PMID 35740680, 2022).
idiopathic pulmonary fibrosis (11 papers, 2009 to 2025). Idiopathic pulmonary fibrosis (IPF) is a nonneoplastic pulmonary disease that is characterized by the formation of scar tissue within the lungs in the absence of any known cause. "Sequence variants in genes for surfactant proteins (SFTPC, SFTPA1, SFTPA2, ABCA3), polymorphisms in MUC5B or TOLLIP, and mutations in telomere genes (TERT, TERC, PARN, and RTEL1) are associated with an increased risk of idiopathic pulmonary fibrosis (IPF)." (PMID 36864460, 2023). "Heterozygous TERC and TERT mutations have also been implicated in cases of idiopathic pulmonary fibrosis (IPF), a chronic progressive lung disease with irreversible fibrosis leading to respiratory failure in most cases within 5 years." (PMID 19419704, 2009).
breast carcinoma (10 papers, 2013 to 2022). "We here investigated the effects of three previously reported functional polymorphisms in the TERT and TERC genes 37, 38, 39, 40 on TL and breast cancer risk." (PMID 28707432, 2017). "The methylation of TERC showed significant association with ER status of breast cancer." (PMID 28424414, 2017). "Our previous study successfully constructed coding sequence optimized GST-TERT and identified that PES1, which expression elevated in many cancers, promoted assembly of TERT and TERC in breast cancer cells." (PMID 35669414, 2022). "The SP1 transcription factor is linked to breast cancer and Huntington's disease, acting together with ATF7IP to maintain telomerase activity via inducing the expression of TERT and TERC." (PMID 32157780, 2020). "The 4 genes (RAD50, RTEL, TERC and TRF1) showed significant hyper-methylation and lower expression in breast cancer." (PMID 28424414, 2017). "The multivariate logistics regression analysis was applied to evaluate the performance of the panel of 4 genes (RAD50, RTEL, TERC and TRF1) as biomarkers for breast cancer prediction." (PMID 28424414, 2017). "The aim of the study was to analyze the consequence of silencing genes coding for the key subunits of the telomerase complex, i.e. TERT, TERC and TP1 in human breast cancer MCF7 and MDA-MB-231cells." (PMID 23677713, 2013).
cervical carcinoma (9 papers, 2005 to 2025). A carcinoma arising from either the exocervical squamous epithelium or the endocervical glandular epithelium. "As we described in our previous study on cervical preneoplastic lesions, TERC gene amplification is a high risk prognostic factor for cervical cancer." (PMID 24410919, 2014). "As described in our previous study on cervical preneoplastic lesions, TERC gene amplification is a high-risk prognostic factor for cervical cancer and is likely an early event in tumorigenesis in squamous cell carcinoma." (PMID 24410919, 2014). "Therefore, identifying the common factors regulated by E6 and TERC might be an important approach to understanding the etiology of HPV‐associated cervical cancer and provide a potential target for cancer therapy." (PMID 35437795, 2022). "Studies in HeLa cells, a cervical cancer cell line, uncovered the interaction between AGO2 and telomerase reverse transcriptase (TERT), as well as the telomerase RNA component (TERC), which promotes TERT and TERC association." (PMID 33668654, 2021). "We used these two same techniques in a study of TERC gene amplifications in cervical cancer, in which we suggested that FISH analysis for TERC amplification should be included in the routine examination of cervical cancer as a screening method." (PMID 24410919, 2014). "Our results, as well those of other authors, obtained from cervical smears have demonstrated that TERC gene amplifications correlate with high-grade squamous intraepithelial lesions that lead to invasive cervical cancer." (PMID 24410919, 2014). "Detection of the TERC gene amplification has been recently proposed as a potential marker for the evaluation of cervical carcinoma progression; however, we detected amplification of the clone representing this gene in less than 10% of the samples analyzed by CGH arrays." (PMID 16004614, 2005). "In summary, TERC gene amplification and HPV have a very close relationship with cervical cancer and precancerous lesions, and its detection can help improve the early screening rate of cervical cancer and provide new directions for cervical cancer treatment." (PMID 32100923, 2020).
osteoporosis (8 papers, 2010 to 2021). A condition of reduced bone mass, with decreased cortical thickness and a decrease in the number and size of the trabeculae of cancellous bone (but normal chemical composition), resulting in increased fracture incidence. "Former study showed that mutational inactivation of the gene WRN and gene TERC (encoding the telomerase RNA component) would lead to telomere dysfunction and cause osteoporosis with low cortical bone mineral density." (PMID 31754224, 2019). "Mutations in the genes associated with the telomerase complex (dyskerin, TERC, TERT, NHP2, and NOP10) are also associated with dyskeratosis congenita, an accelerated aging syndrome, characterized by greying, dental loss, osteoporosis, and malignancy." (PMID 33805567, 2021). "We evaluated the effect of common variants in the telomerase RNA component (TERC) gene on telomere length (TL) in the population-based Health Aging and Body Composition (Health ABC) Study and in two replication samples (the TwinsUK Study and the Amish Family Osteoporosis Study, AFOS)." (PMID 20885959, 2010).
melanoma (7 papers, 2013 to 2023). A malignant, usually aggressive tumor composed of atypical, neoplastic melanocytes. "Some telomere length maintenance genes (TERC, OBFC1) regulate both nevus count and melanoma risk, while the majority regulate melanoma risk only (such as TERT, DKK2, NAF1)." (PMID 36834954, 2023). "In the GWAS-PW analysis combining melanoma and telomere length (TL), there was considerable locus overlap, while by contrast only TERC was detectably shared between nevus count and TL." (PMID 30429480, 2018). "For example, variants in TERC and OBFC1 affect both traits, but other telomere length maintenance genes seem to affect melanoma risk only." (PMID 30429480, 2018). "The telomere-associated SNPs in TERC, TERT, OBFC1, and RTEL1 are near (8-150kb from) SNPs strongly associated with melanoma risk (rs12696304 in TERC, P = .0001; rs455433 in TERT, P = 2.26x10-16; rs2995264 in OBFC1, P = 7.10x10-6; rs75691080 in RTEL1, P = 1.02x10-6) (available online)." (PMID 25231748, 2014). "The fact that only TERC (and OBFC1) are associated with nevus count, while multiple loci are associated with melanoma, is not necessarily surprising." (PMID 30429480, 2018).
type II diabetes (7 papers, 2017 to 2025). "According to the results of Al Khaldu and co-authors, the genotype of TERC gene rs12696304 GG was associated with a 1.6-fold increased probability of developing type 2 diabetes (OR: 1.6, (95% CI: 1.5–1.9), p = 0.005)." (PMID 37762804, 2023). "Based on haplotype analysis, Maubaret and colleagues found that the TERC rs12696304-G-rs10936601-T-rs16847897-C haplotype was statistically significantly associated with a 1.35-fold reduction in the risk of developing type 2 diabetes (OR: 0.74, (95% CI: 0.61–0.91), p = 0.004)." (PMID 37762804, 2023). "Elevated TERC expression was also correlated with chronic inflammatory diseases such as type II diabetes and multiple sclerosis, where both TERC and its target genes are overexpressed." (PMID 40025596, 2025). "The expression levels of TERC in CD14+ cells from type II diabetes and multiple sclerosis patients were significantly higher than normal people." (PMID 31294790, 2019). "On the other hand in a study of the associations of TERC SNPs with LTL and the risk of type 2 diabetes mellitus in Kuwaiti population it has been found that homozygous carries of less common allele (G) of rs12696304 have shorter LTL compared with other genotypes." (PMID 34824901, 2021). "Moreover, we observed that in patients with chronic inflammation such as Type II diabetes and multiple sclerosis, the expression of TERC is upregulated." (PMID 31294790, 2019). "In vivo, expression levels of TERC and TERC target genes (TYROBP, TPRG1L and USP16) are upregulated in patients with inflammation-related diseases such as type II diabetes and multiple sclerosis." (PMID 31294790, 2019).
Cirrhosis (6 papers, 2013 to 2024). A chronic disorder of the liver in which liver tissue becomes scarred and is partially replaced by regenerative nodules and fibrotic tissue resulting in loss of liver function. "The mutations of telomerase RNA component (TERC) sabotaged their enzymatic activity and reduced telomere length among patients with cirrhosis caused by NAFLF, ALD, or HCV infection." (PMID 39735642, 2024). "The study additionally reveals the existence of TERT and TERC mutations among individuals who have been clinically diagnosed with hepatic cirrhosis." (PMID 37720239, 2023). "According to the Calado study, there was a greater incidence of gene variants in the TERT and TERC genes among individuals with cirrhosis compared to the control group." (PMID 37720239, 2023). "There is an increased incidence of TERT and TERC variants in patients with cirrhosis and hepatocellular carcinoma." (PMID 36311538, 2022). "More recently, constitutional “loss-of-function” type of telomerase (TERT or TERC genes) mutations have been identified as a risk factor for cirrhosis." (PMID 23691139, 2013). "Ad transduction also improved hepatocyte proliferation in TERC−/− mice to a level comparable to that of TERC+/+ mice, showing that hepatic damage- and telomere attrition-mediated worsening of cirrhosis can be reversed by TERC gene transfer." (PMID 31035374, 2019). "Similarly, two studies investigated the frequency of telomerase mutations in patients with sporadic cirrhosis compared to healthy controls and demonstrated mutation missense mutations in the Telomerase Reverse Transcriptase (TERT) and TERC genes in diseased patients." (PMID 38349865, 2024).
bladder cancer (5 papers, 2016 to 2025). "The combination of the two plasmids (each targeting either TERT or TERC) led to the strongest bladder cancer growth inhibition, but the underlying mechanism behind this strong combinatory effect was not elucidated in this report and requires further exploration." (PMID 31035374, 2019). "Among these three techniques compared in urine from 200 bladder patients, the sensitivity of TERT mRNA, TERC, and telomerase activity for detecting bladder cancer were 96%, 92%, and 75%, respectively." (PMID 40151802, 2025). "In support, the plasmid-based delivery of shRNA targeting either TERT or TERC led to durable suppression of bladder cancer cell growth up to 6 days after treatment." (PMID 31035374, 2019). "A study from 200 bladder patients comparing these three methods in urine revealed that sensitivity f of TERT mRNA, TERC, and telomerase activity for detecting bladder cancer was 96%, 92%, and 75%, respectively." (PMID 27240403, 2016). "Recently, telomerase activity, TERT mRNA, and TERC telomerase RNA were measured in urine of bladder cancer patients with various sensitivities and specificity rates." (PMID 27240403, 2016). "Furthermore, urinary exosomal TERC expression could distinguish between urinary benign diseases (inflammation, stones, and obstruction) and bladder cancer (P < 0.0001)." (PMID 35127956, 2022). "Recently, excreted urine from bladder cancer patients was tested for telomerase activity, TERT mRNA, and TERC telomerase RNA with a range of sensitivities and specificities." (PMID 40151802, 2025).
bone marrow failure (5 papers, 2014 to 2024). "Here, we report the association of an H-box mutation of TERC with human disease in a young man with bone marrow failure." (PMID 24948335, 2014). "In this study, we have identified a mutation A377G (AGAGGA → AGAGGG) in the H box of TERC in a young patient with bone marrow failure." (PMID 24948335, 2014). "Identification of the constellation of findings (liver abnormalities, cytopenias, premature graying of the hair) consistent with rare genetic mutations in TERT or TERC mutations is critical, as these patients are at risk for bone marrow failure and cryptogenic liver cirrhosis." (PMID 26400796, 2015). "Bone marrow failure is the most common feature in patients with DC and the predominant cause of death and is a common single clinical manifestation in patients with telomere biology gene mutations, especially in the TERT, TERC, and RTEL1 genes." (PMID 36311538, 2022).
colorectal cancer (5 papers, 2015 to 2024). A primary or metastatic malignant neoplasm that affects the colon or rectum. "As for the molecular mechanism of PUS involvement in cancer, it has been reported that overexpression of DKC1 increased the expression of TERC and rRNA pseudouridylation, promoting the proliferation of colorectal cancer." (PMID 36437949, 2022).
Hypertension (5 papers, 2020 to 2025). The presence of chronic increased pressure in the systemic arterial system. "Associations of TERC variants with LTL, and with hypertension and CHD were reported in the general population." (PMID 36221106, 2022). "This study explored the polymorphic alleles of TERC and TERT gene in parents-newborn (triad) and its association with telomere length (TL) and parental diseases (mother: Gestational Diabetes Mellitus (GDM), Preeclampsia, fathers: Diabetes, Hypertension)." (PMID 38192544, 2024). "Therefore, this study aimed to associate the polymorphisms of telomerase gene (TERC and TERT) in parents-newborn (triad) with telomere length and parental diseases (mother: Gestational Diabetes Mellitus(GDM) and preeclampsia, fathers: Diabetes and Hypertension)." (PMID 38192544, 2024). "This study is the first to report TERC (rs10936599) and TERT (rs2736100) gene variations in parents and their newborns, revealing that the homozygous C/C genotype is prevalent in chronic diseases like diabetes and hypertension." (PMID 41168774, 2025).
leukemia (5 papers, 2019 to 2023). A malignant (clonal) hematologic disorder, involving hematopoietic stem cells and characterized by the presence of primitive or atypical myeloid or lymphoid cells in the bone marrow and the blood. "Moreover, G0/G1 phase arrest in HL-60 (leukemia) is also associated with a decrement of telomerase activity as well as TERT and TERC levels." (PMID 33450878, 2021). "Knocking out TERC in mouse can induce cell cycle arrest and apoptosis of leukemia stem cells, while knocking down TERT in AML cells isolated from leukemia patients can gain similar results." (PMID 38111043, 2023).